TLR7 (toll like receptor 7)
Diseases named in the same sentence as TLR7 in open-access papers (continued):
Sharing a sentence is not in itself a finding about the gene and the disease.
tumor (continued). "In addition, the abnormal TLR7 expression was associated with Mismatch repair (MMR), microsatellite instability (MSI), tumor mutational burden (TMB) in various cancers." (PMID 37362864, 2023). "Here the authors show that macrophage-derived microparticles modified with a M2-like macrophage targeting peptide and loaded with the TLR7/8 agonist resiquimod reprogram TAMs from immunosuppressive to inflammatory, promoting anti-tumor immune responses in preclinical HCC models." (PMID 37704614, 2023). "In addition, intravenous injection of a self-assembling nanoparticle vaccine platform co-delivering tumor antigen and TLR7/8 agonist (SNP-7/8a) resulted in a higher frequency of CD8+PD-1+TCF-1+ cells and a significant tumor growth inhibition." (PMID 37704614, 2023). "However, in terms of expanding application to other cancer types and anti-tumor immunity to metastatic tumors, the development of systemically administered TLR7 agonists is expected." (PMID 36793737, 2023). "Mechanistically, TLR7/8 agonists were shown to enhance maturation of MDSCs and/or M2 macrophages, promoting their conversion to APCs and M1-like macrophages and resulting in stimulation of tumor-specific T cell responses." (PMID 37112730, 2023). "The first one21 reported that treatment of p48Cre; KrasG12D (KC) mice with the TLR7 agonist ssRNA40 strongly accelerated tumor progression, while TLR7 inhibition with IRS‐954 was able to block caerulein‐induced inflammation‐mediated tumor progression in KC mice." (PMID 36602302, 2023). "In addition, many clinical trials (phase I-III) evaluate the activation of pDCs in the tumor using TLR7 and TLR9 agonists—which reactivate their production of type I IFN and cytotoxic molecules (e.g., TRAIL)." (PMID 37190135, 2023). "Furthermore, we demonstrated that sEV-miR-574-5p functions as a TLR7/8 ligand in both tumor entities but induced different physiological processes in the tumor environment." (PMID 37731742, 2023). "In addition, the use of imiquimod (IMQ, TLR7 agonist) in a humanized melanoma mouse model inhibited tumor progression following the mobilization of pDCs and the induction of their cytotoxic functions." (PMID 37190135, 2023). "Moreover, R9 can be cleaved at high concentrations of MMP-2 in tumour cells to separate TLR7/8a imidazoquinoline from AuNPs." (PMID 37514054, 2023). "Similarly, the anti-tumor outcome of TLR7 activation was evident in central nervous system tumors, increasing maturation of DCs and activating tumor specific cytotoxic CD8+ T cells." (PMID 37936697, 2023). "Furthermore, anti-CD200R agonists have proven effective in reshaping the tumor microenvironment and improving the anti-tumor effects of other immunotherapies, such as TLR7 agonists." (PMID 38137547, 2023). "Conversely, inhibition of TLR7 in the same cell lines reduced cell viability in a dose‐dependent manner, indicating that TLR7 is not only expressed and functional in the tumor cells but also active, which hints at the presence of effective endogenous ligands and autocrine signaling mechanisms." (PMID 36602302, 2023). "While there is some argument concerning the expression of TLR7 and 8 on NK cells, several reports depicted the activation and proliferation of NK cells by the cytokines secreted from neighboring cells of the tumor microenvironment." (PMID 37936697, 2023). "It is worth noting that TLR7/8 activation has been found to influence the differentiation of myeloid-derived suppressor cells (MDSCs) towards M1 phenotype within the tumor microenvironment, ultimately resulting in a regression of colorectal tumors in mice and a decrease in resistance to oxaliplatin." (PMID 37936697, 2023). "In contrast, global TLR7 deficiency did not alter survival or overall histopathological tumor features in genetic mouse models of PDAC." (PMID 36602302, 2023). "Additionally, alongside TLR9, TLR7 has been identified as a pivotal regulator in tumor progression and is highly regulated in human HCC tissue." (PMID 37822929, 2023).
tumor (continued). "Thirdly, we could not establish a direct causal link, although we discovered a correlation between TLR7 expression and patient survival in some tumor patients and that TLR7 altered immune cell infiltration." (PMID 37362864, 2023). "Effective TLR7/8 agonists targeting the tumor microenvironment (TME) have been successfully delivered using LNPs by targeting the mannose receptor on M206-like macrophages, reprogramming them to an anti-tumor phenotype and boosting NK and T cell killing ability." (PMID 37808190, 2023). "Here, we report DSP-0509 as a novel intravenous injectable small molecule TLR7 agonist which is designed to be rapidly excrete from body to reduce side effects as well as strong anti-tumor activity additively or synergistically combined with immune checkpoint blockers." (PMID 36793737, 2023). "In the lung tumor mouse models, injection of TLR7 agonists increased intratumoral infiltration by MDSCs which could indirectly contribute to the pro-tumoral effects of TLR7 stimulation of tumor cells." (PMID 36476317, 2022). "In addition to targeting many metabolic genes, the exosomal miR-29 derived from β-cells, also found in tumor exosomes, also induces TLR7-MyD88 dependent inflammatory cytokine production, including IFN-I responses." (PMID 35320943, 2022). "Indeed, a single IT administration of TransCon TLR7/8 Agonist was sufficient to induce robust and persistent anti-tumor activity, while also inducing significantly lower systemic cytokine/chemokine release compared to administration of soluble resiquimod." (PMID 36123697, 2022). "Furthermore, TLR7 expressed by malignant cells promotes tumor progression and metastasis through the recruitment of myeloid-derived suppressor cells in NSCLC." (PMID 36476317, 2022). "Additionally, TLR7/8 agonists markedly improved the antitumor activity of PD-1/PD-L1 blockade and led to complete tumor regression." (PMID 36476317, 2022). "Taken together, the described studies provide proof of principle that a single dose of TransCon TLR7/8 Agonist mediates anti-tumor efficacy via sustained delivery of resiquimod to the tumor site while avoiding high systemic exposure and reducing the risk of AEs." (PMID 36123697, 2022). "We hypothesized that coupling tumor-targeting drugs with TLR7 agonists could attract and lead immune cells to the tumor microenvironment, specifically stimulate local immunity and simultaneously kill cancer cells." (PMID 34975325, 2022). "Treatment with R848 (an agonist of TLR7 and TLR8)-loaded β-cyclodextrin NPs (CDNP-R848) can drive M1 polarization of tumor-associated macrophages (TAMs) in the TME in multiple mouse tumor models (e.g., tumors caused by mouse colon adenocarcinoma cell line MC-38 and melanoma cell line B16-F10)." (PMID 36015256, 2022). "Co-delivery of an mRNA vaccine and an adjuvant (R848, a novel TLR7/8 agonist), for example, provided concurrent stimulation of both innate and adaptive immune responses with minimal toxic side effects in a syngeneic allograft mouse tumor model." (PMID 36291194, 2022). "Similarly, TLR7/8 agonist-based tumor vaccines also demonstrated better therapeutic efficacy in combination with PD-L1 blockade in murine tumor models." (PMID 36224474, 2022). "Given that the recognition of TLR ligands can enhance antigen cross presentation in DCs, it is likely that heat-inactivated influenza more potently engaged TLR7, leading to an increase in cross-presenting DCs within the tumor and the activation of CD8+ T cells and thereby reduced tumor progression." (PMID 35740589, 2022). "Consistent with this hypothesis, we observed an increase in the frequency of tumor-antigen-specific CD8 T cells with TransCon TLR7/8 Agonist." (PMID 36123697, 2022). "In addition, TLR7 expressed by tumor cells play roles in promoting tumor progression in both mouse and humans." (PMID 36476317, 2022). "As monotherapy, TransCon TLR7/8 Agonist mediated tumor growth inhibition." (PMID 36123697, 2022).
tumor (continued). "Earlier preclinical studies suggested that repeated systemic resiquimod exposure may lead to TLR tolerance and impaired anti-tumor responses as typified by significantly reduced systemic cytokine release and hyporesponsiveness in TLR7-expressing myeloid cells." (PMID 36123697, 2022). "Furthermore, TLR7/8 agonists as potential therapeutics for tumor-targeted immunotherapy have been developed." (PMID 36476317, 2022). "Immunologically “cold” tumors, such as pancreatic and prostate, may benefit from TransCon TLR7/8 Agonist therapy via innate immune cell activation, promotion of tumor antigen presentation, and recruitment of tumor-specific cytolytic T cells to the TME." (PMID 36123697, 2022). "C57BL/6 mice, B cell knockout (KO) C57BL/6 mice, anti-CD19, and anti-CXCL13 antibody-treated C57BL/6 mice were used to determine treatment efficacy and generation of tumor-specific CD8+ T cells in response to PD-L1 blockade alone or combination with TLR-7/8 activation." (PMID 35720386, 2022). "Given the observed activation of B cells following TransCon TLR7/8 Agonist treatment, an enhanced production of anti-tumor antibodies may contribute to anti-tumor activity and warrants further investigation." (PMID 36123697, 2022). "Importantly, TransCon TLR7/8 Agonist therapy led to an increased frequency of granzyme-positive, and lower frequency of PD-1 positive, tumor-infiltrating CD8 T cells." (PMID 36123697, 2022). "Moreover, a polydopamine nanomedicine was simultaneously loaded with carbon dots, a fluorescent agent and the ROS-responsive TLR7/8 agonist resiquimod (R848) to treat 4T1 tumor-bearing mice." (PMID 35335881, 2022). "In a syngeneic murine tumor model, TransCon TLR-7/8 agonist elicited sustained expression of cytokines and inflammatory chemokines in the tumor but with low levels in plasma, promoted sustained expression of peripheral B, T and KN cells, and was associated with a potent antitumor response." (PMID 35449104, 2022). "However, intratumoral administration of a TLR7 agonist induced pDC activation and inhibited tumor growth through modulation of Tregs." (PMID 35806328, 2022). "Because immune infiltration inside tumour tissues indicates an adequate anti-tumour immune response, high TLR7 and TLR8 expression may predict a better patient prognosis, providing support for a wide range of immune therapies targeting TLR7 and TLR8." (PMID 35801728, 2022). "When squamous cell carcinoma samples were treated with a toll-like-receptor-7 agonist, imiquimod, up-regulated tumor vessels E-selectin expression was found on previously E-selectin negative tumor-associated vessels." (PMID 35663420, 2022). "The data presented suggest TransCon TLR7/8 Agonist may promote both innate and adaptive immune cell-driven anti-tumor activity." (PMID 36123697, 2022). "We hypothesize that a different and more physiological setting is needed in order to evaluate the impact of TLR7-mediated angiogenic modulation on tumor growth in vivo." (PMID 33578955, 2021). "TLR7 is generally accepted to play a pivotal role in the tumor microenvironment." (PMID 33982398, 2021). "Additionally, TLR7/8 agonist MEDI9197 combined with immune checkpoint inhibitors PD-1 blockade can polarize TAMs toward anti-tumor phenotypes and activate CD8+ T cells and NK cells, leading to a better efficacy." (PMID 34178692, 2021). "Moreover, TGFβ is also able to synergize with tumor-derived prostaglandin E 2 (PGE2) to abrogate IFNα production by purified human pDCs in response to different TLR7/9 stimuli." (PMID 33919546, 2021). "Similarly, therapy that combined dendritic cell-based tumor vaccine with toll-like receptor 7 (TLR7) agonist showed excellent anti-tumor response that resulted in a decrease of tumor infiltrating Tregs." (PMID 34806028, 2021). "This evidence suggests that the TLR7 functions in cancer progression are complex and might be dependent on the tumor context." (PMID 33578955, 2021).
tumor (continued). "The expression of BDCA-2, CD103, and TLR7 was heterogeneous in different tumor localizations." (PMID 34573939, 2021). "Several studies have reported that the agonists of TLR7 could prevent tumor recurrence and eliminate metastasis." (PMID 34856991, 2021). "TLR7 (toll-like receptor 7) agonist MEDI9197 could modulate the tumor microenvironment leading to enhanced activity when combined with other immunotherapies." (PMID 34404444, 2021). "Aware of the limits of the method, which does not discriminate the expression of TLR7 between different cell types (tumor or stroma), we asked whether TLR7 expression levels correlate with NSCLC patients’ clinical attributes." (PMID 33578955, 2021). "Resiquimod (R848) is a TLR7/8 agonist that has shown antitumor activity in murine tumor models." (PMID 34959344, 2021). "Dysregulation of the tumor immune microenvironment affected by TLR7 overexpression might be responsible for the poor prognosis of STAD." (PMID 33982398, 2021). "The authors suggested that the engagement of multiple receptors, such as TLR7/8/9, may be necessary for improving the host anti-tumor response." (PMID 33669782, 2021). "pDCs express high levels of TLR7/9 which upon recognition of viral DNA/RNA produce type I interferons (IFNs) and induce NK and macrophage activation (innate immune response) and T-cell expansion (adaptive immune response) to promote tumor cell lysis." (PMID 34715891, 2021). "IMQ is an established TLR7 agonist that can be used in tumor immunotherapy." (PMID 33431816, 2021). "For instance, muscle-specific activation of TLR7 by tumor-secreted microvesicles promotes skeletal muscle cell death, while local activation of TLR7 in the tumor stroma triggers CD8+ T-cells, resulting in tumor shrinkage and, consequently, in reduced cachexia and improved survival." (PMID 33419963, 2021). "The protumorigenic effect could be mediated either by the direct stimulation of TLR7-expressing tumor cells or by the increased recruitment of immunosuppressive cells in the TME, such as myeloid-derived suppressor cells (MDSCs) and a reduction of CD8 T cells." (PMID 34209514, 2021). "It has been well established that immune checkpoints negatively regulate the anti‐tumor immunity of the body, and TLR7 might attenuate the anti‐tumor immune response by increasing the expression of immune checkpoints." (PMID 33982398, 2021). "We hypothesized that TLR7 could promote an immune suppressive microenvironment that enhances the resistance of tumor cells and promotes immune evasion." (PMID 34209514, 2021). "Collectively, HJ901 treatment may have reduced IL-6 and IL-10 secretion in cells and suppressed cell proliferation and tumor growth in cells and mice through possible mechanisms that modulate the TLR7/9, NF-κB, and JAK2-STAT3 signaling pathways." (PMID 32391356, 2020). "In this study, HJ901, a synthetic ODN containing a sequence with CCT repeats, was found to exhibit a specific inhibitory role in TLR7/9 activation-induced innate immune responses and in reducing cell proliferation and tumor growth in ABC-DLBCL cell lines expressing the MyD88 L265P mutation." (PMID 32391356, 2020). "However, the detailed molecular mechanisms by which TLR7/8 support antigen presentation by dendritic cells and promote anti-tumor T cell response are largely unclear." (PMID 32961746, 2020). "In a syngeneic orthotopic mouse model, TLR7/8 agonist 3M-011 stimulated antigen presentation by dendritic cells following local radiotherapy, thereby boosting systemic and local immune-mediated tumor rejection." (PMID 32961746, 2020). "EV-lncRNA-FMR1-AS1 from esophageal carcinoma stem cells could stimulate stemness of recipient cancer cells and in vivo tumor growth by binding TLR7." (PMID 32503543, 2020). "For example, TLR7/8 expressed on tumor cells may bind DAMPs (loxoribine for TLR7, and poly U for TLR8) and promote chemoresistance through the activation of NF-κB and the upregulation of BCL2." (PMID 32817793, 2020).
tumor (continued). "Modification of SZU-106 that can increase SZU-106 activity as TLR7 agonist may be needed to further improve the immunogenicity of our whole-cell tumor vaccine, while reduce the side effects brought by SZU-106 as much as possible." (PMID 32922200, 2020). "TLR7, a dual receptor for guanosine and uridine-containing ssRNA in innate immunity, could perform tumor-suppressive activity by mediating the activation of NFκB and inducing proinflammatory cytokines." (PMID 32717065, 2020). "Similarly, an impressive systemic anti-tumor immune response was elicited by irreversible electroporation (IRE) of local PDAC tumors that were co-treated with an intratumoral TLR7 agonist (1V270) and systemic anti-PD-1 receptor checkpoint blockade." (PMID 32961746, 2020). "Tumor-derived EV-miR-21 promotes apoptosis of skeletal muscle cells by activating TLR7." (PMID 32503543, 2020). "However, higher TLR-7 was correlated with tumour site (p = 0.004), regional metastasis (p = 0.001) and advanced stages (p = 0.003) in patients with OPSCC." (PMID 33008143, 2020). "We report that activation of TLR7/8 in the tumor results in sustained transformation of the TME." (PMID 31511088, 2019). "Based on the differential effects we observed depending on whether TLR7 was present in tumor stroma, we investigated the frequency of R848-responsive genes in tumor compartments using an RNA-seq library of laser-capture microdissected human pancreatic lesions." (PMID 31615993, 2019). "Thus, it will be of interest to determine if, like tumor-released DNA, tumor-released RNA can also facilitate the adjuvant effect of chemotherapy by behaving as an agonist of TLR7 or TLR8 signaling." (PMID 31619293, 2019). "One strategy to turn an immunologically cold tumor hot is to promote activation of antigen presenting cells (APC) by targeting the endosomal TLRs TLR3, TLR7, TLR8, TLR9, or by targeting the ER-associated signalling molecule stimulator of interferon genes (STING)." (PMID 31511088, 2019). "Althoughour earlier results indicated that epithelial factors mediate R848 response, the changes in immune complexity of treated tumors led us to hypothesize that R848-induced tumor immunity also requires stromal TLR7." (PMID 31615993, 2019). "Moreover, we demonstrate that the anti-tumor effects of this TLR7/8 agonist can be enhanced through combination with checkpoint inhibitors and co-stimulatory agonists." (PMID 31511088, 2019). "After establishing evidence of benefit for both tumor burden and cachexia severity, we determined whether the effects of R848 in the tumor microenvironment were dependent on stromal or neoplastic cell TLR7." (PMID 31615993, 2019). "In this study, we investigated whether the TLR7/8 agonist R848 elicits anti-tumor responses in syngeneic orthotopic (OT) murine PDAC models and whether this class of therapy is beneficial or harmful toward PDAC-associated cachexia." (PMID 31615993, 2019). "Indeed, TLR7 agonists have previously been reported to enhance efficacy in combination with radiotherapy and chemotherapy in syngeneic mouse tumor models." (PMID 31511088, 2019). "Moreover, we revealed how TLR7 agonists alter the tumor immune microenvironment using a combination of quantitative multiplex immunohistochemistry (mIHC) and flow cytometry." (PMID 31615993, 2019). "Recent reports demonstrated that intratumoral injection of a phospholipid-conjugated TLR7 agonist increased the ratio of M1/M2 TAMs in several tumor models, and subcutaneous injection of resiquimod in CT26 tumors converted monocytic MDSCs into non-suppressive state." (PMID 29568358, 2018). "Our group has a strong background in researching tumor vaccines with applications of TLR7 agonists." (PMID 29739434, 2018). "In addition, adding TLR3 and TLR7 agonists to a DNA vaccine containing the HPV16 E7 sequence promoted significant tumor regression in mice." (PMID 30328949, 2018).